IFNA5 (interferon alpha 5)
Description:
Produced by macrophages, IFN-alpha have antiviral activities. Interferon stimulates the production of two enzymes: a protein kinase and an oligoadenylate synthetase.
Synonyms: IFN-alpha-5; LeIF G; IFN-alphaG; INA5; INFA5
Tractability: Antibody: a drug acting on it is in phase 2 or 3 trials; its Gene Ontology location is reachable by antibodies, with high confidence; UniProt places it where antibodies can reach, with medium confidence; UniProt predicts a signal peptide or a membrane-spanning region.
Gene: Protein-coding gene on chromosome 9 (21,304,326 to 21,305,313, reverse strand). Ensembl gene ENSG00000147873.
Subcellular location: Secreted
Pathways (Reactome):
Immune System: Interferon alpha/beta signaling; Regulation of IFNA/IFNB signaling; TRAF6 mediated IRF7 activation
Disease: Evasion by RSV of host interferon responses; SARS-CoV-2 activates/modulates innate and adaptive immune responses
Hemostasis: Factors involved in megakaryocyte development and platelet production
Gene Ontology:
Molecular function: cytokine activity; cytokine receptor binding; type I interferon receptor binding
Biological process: adaptive immune response; B cell activation involved in immune response; cellular response to virus; humoral immune response; natural killer cell activation involved in immune response; response to exogenous dsRNA; T cell activation involved in immune response; type I interferon-mediated signaling pathway; defense response
Cellular component: extracellular region
Genetic constraint (gnomAD): Loss-of-function variants: 0 observed, 0.23 expected, observed/expected ratio (o/e) 0, 90% interval 0 to 1.87. That is too few expected variants to judge how well the gene tolerates losing a copy. Missense variants: 267 observed, 218.7 expected, observed/expected ratio (o/e) 1.22, 90% interval 1.1 to 1.35. Synonymous variants: 95 observed, 80.4 expected, observed/expected ratio (o/e) 1.18, 90% interval 1 to 1.4.
Homologues: Orthologues: chimpanzee IFNA5 (98% identical), pig IFN-ALPHA-15 (69% identical), pig IFN-ALPHA-9 (69% identical), pig IFN-ALPHA-8 (68% identical), pig IFN-ALPHA-13 (68% identical), pig IFNA1 (67% identical), pig IFN-ALPHA-4 (66% identical), pig IFN-ALPHA-17 (65% identical), rabbit IF1AD2 (65% identical), pig IFN-ALPHA-1 (64% identical), pig IFN-ALPHA-10 (64% identical), rabbit IF1AD7 (64% identical), and 31 more. Paralogues in human: IFNA21 (87% identical), IFNA6 (86% identical), IFNA13 (85% identical), IFNA14 (85% identical), IFNA1 (84% identical), IFNA2 (84% identical), IFNA4 (84% identical), IFNA10 (83% identical), IFNA16 (83% identical), IFNA17 (83% identical), IFNA8 (82% identical), IFNA7 (80% identical), and 4 more.
Diseases named in the same sentence as IFNA5 in open-access papers:
IFNA5 is named in the same sentence as 13 diseases in open-access papers, as found by Europe PMC text mining. Sharing a sentence is not in itself a finding about the gene and the disease. The quoted sentences say what the papers report.
viral infection (6 papers, 2018 to 2025). "Since the type I and III interferon (IFN) responses are the earliest host responses to be triggered upon viral infection, we next measured the gene expression of Ifna5, Ifnb, and Ifnl in lung tissue." (PMID 38742107, 2024). "As expected, the strongest reduction in viral titers was observed upon pretreatment with IFNα5 as cells become alerted toward an antiviral state, and antiviral effectors can be transcribed or even translated prior to viral infection." (PMID 35131898, 2022). "Intriguingly, even after viral infection was established, treatment with IFNα5 was able to significantly reduce viral titers, which was also observed with the antiviral drug remdesivir." (PMID 35131898, 2022). "To better understand the response of microglia after virus infection, we investigated the IFNB1, IFNA1, and IFNA5 expression at the MOIs 0.1, 0.01, and 0.001, where the viability was near 50% after infections at 3 DPI." (PMID 38213031, 2024). "We found no expression of IFNA1 and IFNA5 (data not shown), and dose-dependent IFNB1 expression after virus infection, indicating innate immune signaling activation." (PMID 38213031, 2024). "In contrast, the strongest biological effects on antiviral immune responses after treatment with IFNα5 and IFNλ3, for example, IFN signaling as well as antigen presentation, nuclear factor κB signaling, or lymphocyte regulation, were not affected by viral infection." (PMID 35131898, 2022).
COVID-19 (2 papers, 2021 to 2022). A disease caused by infection with severe acute respiratory syndrome coronavirus 2. "Despite these low baseline levels, among the 7 IFNA subtypes examined we did observe some subtype differences, with notably higher levels of IFNA6 and IFNA5 in both COVID-19 patient groups and IFNA1/13 only in the hospitalized group." (PMID 36434007, 2022).
Autoimmunity (1 paper, 2023). The occurrence of an immune reaction against the organism's own cells or tissues. "We here provide further insights into the intrarenal expression of type I interferons and show that tubulointerstitial IFNA5 expression might be relevant specifically in lupus nephritis autoimmunity." (PMID 37445814, 2023).
glomerulonephritis (1 paper, 2021). A renal disorder characterized by damage in the glomeruli. "In contrast, overexpression of SHP-1 further ameliorated the severe glomerulonephritis caused by IFNα5." (PMID 34535085, 2021). "In this study, histologic examination (PAS staining) revealed that IFNα5 adenovirus-treated (NZB × NZW)F1 mice developed severe glomerulonephritis." (PMID 34535085, 2021).
lupus nephritis (1 paper, 2023). Glomerulonephritis in the context of systemic lupus erythematosus. "In summary, proteinuria was associated with intrarenal expression of type I interferon IFNA5 in lupus nephritis." (PMID 37445814, 2023). "Here we pursued a transcriptome array-based approach and linked proteinuria to the intrarenal expression of type I interferon IFNA5 in lupus nephritis." (PMID 37445814, 2023). "Next, we characterized tubulointerstitial and glomerular type I interferon IFNA5 expression with regard to clinical and laboratory parameters in lupus nephritis." (PMID 37445814, 2023). "This aligns with our observation that IFNA5 is predominantly expressed in the tubulointerstitial compartment in lupus nephritis." (PMID 37445814, 2023). "In summary, this transcriptome array-based approach links proteinuria to the tubulointerstitial expression of type I interferon IFNA5 in lupus nephritis." (PMID 37445814, 2023). "Although we are aware that these observations require further validation in experimental models, we here provide the first evidence to link proteinuria and intrarenal expression of type I interferon IFNA5 in lupus nephritis." (PMID 37445814, 2023).
melanoma (1 paper, 2020). A malignant, usually aggressive tumor composed of atypical, neoplastic melanocytes. "This was systematically evaluated by transplantation of B16 murine melanoma cells secreting five unique IFNα subtypes (B16_IFNα2; B16_IFNα4; B16_IFNα5; B16_IFNα6; B16_IFNα9) into a pre-clinical murine model." (PMID 32308653, 2020). "In addition, the secreted IFNα4, IFNα5, and IFNα9 could upregulate H-2Kb on both B16_IFNα and WT B16 melanoma cell lines." (PMID 32308653, 2020).
infection (12 papers, 2012 to 2025). The state of being infected such as from the introduction of a foreign agent such as serum, vaccine, antigenic substance or organism. "In the brain, infection with Bov342 induced the expression of type-I (Ifna5, Ifnb), -II (Ifng), and -III (Ifnl2) interferons (IFN), interferon stimulated genes (ISGs) (Isg15, Ifit1, Mx1, Oas1), and pro-inflammatory cytokines (Il1b, Il6, and Tnfa) at endpoint." (PMID 40410375, 2025). "In contrast, Ifna5 mRNA expression peaked at 48 h following infection with either 6:2 Tky/05 or 7:1 Tky/05 LOW virus." (PMID 36226985, 2022). "Furthermore, only infection with Omicron resulted in a significant induction of Ifna5 and Ifnb, ISG-driven antiviral effectors Mx1, Oas1, and Viperin, and pro-inflammatory mediators Cxcl10 and Il6." (PMID 38742107, 2024). "Ifna5 mRNA peaked at 6 h.p.i. following infection with the 7:1 Tky/05 HIGH virus." (PMID 36226985, 2022). "We further determined that D39 infection increased the expression of IFNa5 (subtype of IFN-I) at 5 h, but not 1 h post-infection." (PMID 30984149, 2019).
tumor (2 papers, 2018 to 2020). "IFNα4, IFNα5, and IFNα6 had the remarkable capacity to delay tumor growth for well-over 100 days." (PMID 32308653, 2020).
IFNA5 also shares sentences with these, for which no sentence is quoted: bronchiolitis (1 paper); cancer (1); HIV-1 infection (1); lupus (1); Splenomegaly (1).